TNF (tumor necrosis factor)
Diseases named in the same sentence as TNF in open-access papers (continued):
Sharing a sentence is not in itself a finding about the gene and the disease.
malaria (continued). "Increased TNF, IFN-γ, IL-1, IL-2, IL-6, IL-10, TGF-β, CCL2, CCL3, and G-CSF levels and decreased IL-5, IL-12, IL-17, and CCL11 levels were observed in malaria monoinfection compared to intestinal parasite monoinfection." (PMID 36716305, 2023). "Although TNFα has been proposed as a potential biomarker for severe malaria in non-pregnant individuals, it appears to correlate with protection in the context of pregnancy." (PMID 37634385, 2023). "In contrast, multigravid women had higher percentages of CD4+ T cells that produced TNFα in the absence of IFNγ and IL-10, and these cells were correlated with protection against malaria in pregnancy." (PMID 37634385, 2023). "An analysis of the cord blood revealed that TNF, IL-1β, and IL-5 were associated with severe malaria but IL-4, IL-6, IFN-γ, and IL-10 did not relate to severe malaria." (PMID 36668942, 2023). "Individuals in Southern Ghana carrying the TNF-α 308 GA genotype are more likely to exhibit symptoms of malaria when infected with the malaria parasite as opposed to harboring an asymptomatic infection." (PMID 35291755, 2022). "Kyoto Encyclopedia of Genes and Genomes (KEGG) pathway analysis further revealed that nanoFe upregulated the pathways of nitrogen metabolism and simultaneously downregulated the pathways pertinent to the TNF signaling pathway, influenza A, JAK/STAT signaling pathway, and malaria." (PMID 36064371, 2022). "The advantage of this is that individuals with TNF-α 308 GA would immediately seek treatment for malaria as they would exhibit symptoms and not add to the transmission reservoir of asymptomatic carriers." (PMID 35291755, 2022). "Some investigators have suggested that the balance between pro-inflammatory (TNF-α, IFN-γ, IL-6 and IL-8) and anti-inflammatory (IL-4, IL-10) cytokines determines the degree of malaria parasitaemia, level of anaemia, clinical severity, presentation and outcome." (PMID 34666102, 2021). "Similar to responses seen with DCs from malaria-naïve US donors, mDCs obtained from Malians did not secrete significant amounts of the inflammatory cytokines IL-1β, IL-6 or TNF." (PMID 33407502, 2021). "This is also the case for TNF-α, which was not detectable in the supernatants of endothelial cells stimulated with both plasma from the control and malaria patients." (PMID 34359826, 2021). "The absence of IL-1β and IL-6 and TNFα during CHMI is not unusual as reported in other controlled malaria studies." (PMID 34548530, 2021). "No TNF-α was detected in the supernatants of endothelial cells after stimulation with plasma from the malaria patients or with plasma from the healthy controls, respectively." (PMID 34359826, 2021). "Here, we significantly extend this research by optimizing a blood-stage liposomal vaccine using the P. yoelii rodent malaria model and interrogating the immune response to identify CD4+ T cells, IFN-γ, TNF, and IL-10 as critical mediators of protective immunity." (PMID 34663097, 2021). "Similarly, studies assessing cytokine responses in subjects immunized with vaccines such as hepatitis B, tetanus toxoid or malaria (RTS’S/AS and AMA-1), have shown that TNF and IL-2 are the main cytokines detected following immunization." (PMID 34597297, 2021). "The only clear correlation between Malaria-related inflammatory cytokine levels and EBV reactivation, as reflected by increased EBV-DNA levels, was found for TNF-α (R2 = 0.8915) in persons infected with P. falciparum, but not in P. vivax or mixed-infection cases." (PMID 34962938, 2021). "This is likely to be caused by TNF-α since this was absent in LMW challenges at 20 mg/kg and TNF-α has been described to be a key mediator in inducing miscarriage in LPS and malaria models." (PMID 33442686, 2021). "Our study seems to confirm these findings, since we observed significantly elevated mean TNF-α levels in all Malaria cases compared to the healthy controls, irrespective of the type of Plasmodium infection, age or gender." (PMID 34962938, 2021).
malaria (continued). "The increase of TNF-α levels was seen in both male and female Malaria cases, but there was no relation with age." (PMID 34962938, 2021). "Pro-inflammatory chemokines (CXCL10, CCL2, and CCL3) and cytokines (TNF-α, IL-8, and IL-6) were reported to mediate severe malaria and SCD separately but have not been examined in SCD individuals infected with malaria." (PMID 33424841, 2020). "The TLR9 1174 G/A SNP was linked to rapid disease progression in children with malaria and HIV-infected patients and was also associated with nonresponse to anti-TNF treatment among patients with inflammatory bowel disease." (PMID 32753695, 2020). "Additionally, the DEGs enriched into multiple KEGG pathways, including cell adhesion molecules (CAMs), IL-17 signaling pathway, malaria, PI3K-Akt signaling pathway, and TNF signaling pathway." (PMID 32832554, 2020). "Based on our data CXCL10, TNF-α, CCL3, IL-8, and IL-6 may be investigated as potential markers to assess malaria severity and protection." (PMID 33424841, 2020). "It was also determined that malaria outcomes could be altered based on the crosstalk between inflammatory cytokines (CXCL10, CCL3, IL-8, TNF-α, and IL-6) and Hb genotypes." (PMID 33424841, 2020). "A significantly higher level of IFN-γ, TNF-α, IL-6, and IL-10 were expressed by co-infected cases than malaria cases, except for TGF-β which did not vary significantly." (PMID 31687034, 2019). "It has been reported that imbalance of cytokines such as tumor necrosis factor alpha (TNF-α), interleukin-6 (IL-6), IL-10 and interferon gamma (IFN-γ) resulting from malaria related-inflammation can induce changes in iron absorption and distribution (iron delocalization)." (PMID 31760954, 2019). "Also, elevated levels of TGF-β, TNF-α, IL-10, and IL-1β were found in cerebral malaria, while IL-2, IFN-γ, IL-5, IL-6, and IL-12 were only increased in mild malaria." (PMID 31878288, 2019). "Similarly, the Malaria+CHB group had significantly elevated pro-inflammatory cytokines, including tumour necrosis factor alpha (TNF-α), interleukin (IL)-1β, and IL-6 [P<0." (PMID 31002731, 2019). "Thus, the levels of both tissue and plasma IFNγ, TNFα, and IL-6 were assessed in WT and TRPV1KO mice with malaria." (PMID 31223430, 2019). "In a study of acute-phase malaria in young children in Gabon, patients with severe malaria had significantly lower IL-12(p40/p70) and IFN-γ compared to matched controls with mild malaria; in addition, TNF and IL-10 were significantly higher in severe malarial cases." (PMID 31234875, 2019). "BLIMP1-mediated IL-10 production by Tr1 cells was recently reported in experimental malaria, and BLIMP1-dependent IL-10 production by Tr1 cells protected against IFNγ-dependent, TNF-mediated splenic tissue damage, but also limited the control of P. chabaudi AS blood parasitemia." (PMID 30809232, 2019). "The TNF-α level was significantly elevated in co-infection over HAT or malaria mono-infections (P < 0.05) unlike TGF-β level." (PMID 31687034, 2019). "Although P. vivax and P. falciparum malaria patients have similar cytokine profiles during infection, P. falciparum patients presented higher levels of IFN‐γ and TNF‐α, in acute phase and of IFN‐γ, IL‐6, IL‐8, IL‐17, and G‐CSF in convalescent phase than P. vivax patients." (PMID 29314720, 2018). "And lastly TNF-α is probably not involved in modulation of malaria, soil borne helminth and co-infections of both diseases." (PMID 29560020, 2018). "Given that optimal induction of proinflammatory cytokines (e.g., IFN-γ and TNF-α), and the counterbalance exerted by anti-inflammatory cytokines (TGF-β and IL-10) are crucial for determining the outcome of blood-stage malaria, we first analyzed the serum levels of these molecules." (PMID 30462731, 2018). "A correlation matrix revealed a correlation between IL-2 and IL-17F with TNF-α in the OP group, but no other cytokine correlations were detected in the malaria patients and Pf infected children." (PMID 29555909, 2018).
malaria (continued). "Indeed, our previous study demonstrated that blood-stage malaria exhibits anti-tumor effects by inducing a potent anti-tumor innate immune response, including the secretion of IFN-γ and TNF-α and the activation of NK cells." (PMID 28228842, 2017). "Taken together, these results demonstrate that the macrophage pro-inflammatory response to malaria PAMPs in terms of TNF secretion as well as Tnf and Il1b gene transcription is not as pronounced as that elicited by LPS." (PMID 28560184, 2017). "Indeed, only in the younger age group were TNF, IL6, and IL2 concentrations elevated during acute malaria (day 0) as compared to convalescence (week 3)." (PMID 29284469, 2017). "Quantification of levels of pro-inflammatory cytokines, including TNF-α, IFN-γ, IL-1β, IL-2, IL-8, IL-6, IL-12, and GM-CSF in children with malaria in the three transmission areas revealed a pattern of decreasing cytokine levels with increasing transmission intensity (Accra > Navrongo > Kintampo)." (PMID 28399920, 2017). "Three other loci (CR1, TNF, and TLR4) showed borderline associations with the principal component 2 but not with any particular measure of malaria transmission." (PMID 28541483, 2017). "In a study from Kenya, children with severe malaria (the type of severe malaria was not specified) had higher IL-10-to-TNF-α ratios than did children presenting with mild disease." (PMID 28122790, 2017). "All these biomarkers were lower in the second samples confirming the induction of different types of immune mediators including growth factor (G-CSF), inflammatory (TNFα, IL-1α, IP-10), anti-inflammatory (IL-10) and chemokines (IL-8, MCP-1) during immune response to malaria." (PMID 27168977, 2016). "Thus, the PBMC of malaria patients were stimulated with iRBC and their production of IFNγ, IL10, TNFα, and IL13 was measured by intracellular staining." (PMID 27802341, 2016). "In addition, the significant multivariate correlation of EPO, hemopexin and total heme with TNF-α, IL-10, IP-10 and MCP-1 suggests the implication of EPO in the complex network of factors of the immune system influenced by heme during severe malaria." (PMID 27441662, 2016). "Dexamethasone (steroid), antibodies against TNF-α, phenobarbital (anti-convulsant) and iron chelation with desferrioxamine administration in malaria have not yielded expected outcomes." (PMID 27618936, 2016). "Animal studies suggest that TNF-α is directly involved in pathogenesis of severe malaria and is not simply a marker of disease severity." (PMID 27339303, 2016). "Regarding the individual biomarkers, we found pro-inflammatory immune mediators increased in malaria patients with levels of IL-6 and IL-8 higher in CM compared to NCM individuals, and of eotaxin, IL-15, MCP-1 and TNFα elevated in deceased compared to survivors of CM." (PMID 27168977, 2016). "TNF participates in the total IgG response, which is mediated by follicular dendritic cells and dependent on soluble TNFR1 signalling, and high levels of this cytokine are related to malarial paroxysm and severe malaria." (PMID 27435973, 2016). "Kaplan–Meier analysis did not indicate marked group-specific differences in malaria rates for specific time periods of follow-up for either of the two TNF genotypes investigated." (PMID 26088606, 2015). "Severe malaria was also associated with higher levels of IL-1β (p = 0.008), IL-2 (p = 0.001), IL-4 (p = 0.041), IL-12p70 (p = 0.010), IL-13 (p = 0.004), IFN-γ (p = 0.041), TNF (p = 0.049), IFN-γ/IL-10 (p = 0.016), TNF/IL-10 (p = 0.016) and (TNF + IFN-γ)/IL-10 (p = 0.001) than mild malaria." (PMID 26466783, 2015). "Hepcidin was positively correlated with IL-6 (r = 0.4339; p = 0.0015), IL-10 (r = 0.5154; p = 0.0002), and parasitaemia (r = 0.3032; p = 0.0096) and negatively correlated with IFN-γ/IL-10 (r = −0.4369; p = 0.0017) and (TNF + IFN-γ)/IL-10 (r = −0.3776; p = 0.0075) in the mild malaria group." (PMID 26466783, 2015).
malaria (continued). "An important role for TNF and IFN-γ in the onset of malaria symptomatology as well as in pathological processes associated with platelet consumption, endothelial cell activation and haemorrhagic manifestations during dengue fever have been described previously." (PMID 26271921, 2015). "Recent observations in individuals naturally exposed to malaria suggest an important role for CD4+ T cell production of TNFα, with or without IFNγ, as a potential immunologic correlate of protection." (PMID 24415936, 2014). "Host responses mediated by inflammatory cytokines such as TNF, LT-α, IFN-γ and effector cells such as CD4+ and CD8+ T cells, NKT cells and NK cells have been shown to contribute to severe malaria in this model." (PMID 24476686, 2014). "In RTS/S vaccine recipients, malaria-specific CD4+ T cells producing TNFα in the absence of IFNγ or IL-2 have recently been shown to correlate with protection from malaria infection." (PMID 24415936, 2014). "Although studies have described higher levels of circulating TNF-α in P. vivax-infected patients, other different groups reported no induction of this cytokines during malaria." (PMID 24741587, 2014). "Supporting its importance in inflammatory-related processes, HZ-induced TNFα production by human monocytes was found to be inhibited by IgM purified from malaria patients, but not from healthy donors." (PMID 24550911, 2014). "Human pDCs but not mDCs express TLR9 and produce IFN-α and TNF-α in response to malaria parasites and that the robust production of IL-12 requires cooperation of both pDCs and mDCs." (PMID 24204889, 2013). "In addition, soluble cytokines such as tumor necrosis factor (TNF) are known to alter BBB permeability, allowing cytokines and malaria antigens to enter the brain compartment." (PMID 23890318, 2013). "Kaplan-Meier curves indicate that children with high cord levels of IL-1β (but not TNF-α) are protected against severe malaria." (PMID 24130857, 2013). "The predominance of IFNγ and TNFα in the CD8+ T cell response was a feature of all vaccination regimens and has previously been observed following adenoviral-vectored vaccination of BALB/c mice with recombinant malaria parasite antigens." (PMID 24304565, 2013). "The assayed cytokines were detectable in the placental sera (IFN-γ, IL-12, IL-4, IL-6 and IL-10) and plasma (TNF-α) samples extracted from malaria-infected and malaria-negative olive baboons." (PMID 26623293, 2012). "To investigate a potential role for UA in malaria pathogenesis, we first measured the levels of ten cytokines (IL-6, IL-10, MCP-1, sTNFRII, IL-8, IP-10, TNFα, IFNγ, GM-CSF and IL-1β) that other studies have implicated in the development of severe malaria in humans." (PMID 23071567, 2012). "IL-10 and TNF responses to a T cell stimulus were higher in AC than in any of the three clinical malaria groups, suggesting an impaired T cell responsiveness in malaria (regardless of the clinical presentation) as observed by others." (PMID 22853732, 2012). "In that previous report, we were unable to assess polyfunctionality of T cell phenotypes, but nevertheless identified an association between the frequency of CD4+ T cells producing at least TNF on stimulation with CSP peptides and protection against clinical malaria." (PMID 23300801, 2012). "Expansion of macrophages and elevated TNF level are critical for controlling parasitaemia, while IFN-γ forms a central mediator of protective immune responses against pre-erythrocytic and blood-stage malaria parasites." (PMID 22873687, 2012). "However, for the malaria infected, BCG vaccinated mice, dramatic declines in CD8 TNF-α MFI values of >99% were detected in IFN-γ/TNF-α and triple positive CD8 MFT cells at two weeks after the P. yoelii infection." (PMID 22205939, 2011).
malaria (continued). "The effects of polymorphisms in a number of genes, including β-globin, G6PD, TNF-α, IFN-γ, CD36, ICAM-1, IL10, IL4R, and LTA, upon the clearance of malaria parasites in African individuals was investigated across five large association studies from Burkina Faso, Cameroon, Kenya, Mali, and Sudan." (PMID 21867552, 2011). "We then showed for this rodent malaria model that the inhibitory effect observed in vivo was actually mediated by the IL-6 secreted by non-parenchymal liver cells in response to TNF-α stimulation." (PMID 21394207, 2011). "Several studies suggest that the balance between pro- (TNF-α, IFN-γ, IL-8) and anti-inflammatory (IL4, IL-10, TGF-β) cytokines determines the degree of malaria parasitaemia, the level of anaemia, the clinical severity, the presentation, and/or the outcome of infection." (PMID 21867552, 2011). "Lack of association between LTA/TNF/LTB SNPs and severe malaria subgroups when compared with adult and childhood controls in the Papuan population." (PMID 21029472, 2010). "For example association between polymorphisms within the Major Histocompatibility Complex (MHC) region on chromosome 6p21–p23, that contains the Tumor Necrosis Factor alpha (TNF-α) gene, and severe but also mild malaria has been demonstrated in several population in particular in Gambian children." (PMID 20657648, 2010). "Among malaria-infected multigravid women levels of TNF-α and IL-10 in placental blood (but not peripheral blood) were similarly inversely correlated with peripheral Apo-AI (r = −0.453, p = 0.011, n = 24; r = −0.392, p = 0.036, n = 22 respectively)." (PMID 20098675, 2010). "This study found an association of iron deficiency anaemia with slightly reduced concentrations of IL-1β, IFN-γ and TNF in children without malaria but an increment in children with malaria infection." (PMID 20546583, 2010). "Our results indicated significantly higher TNF levels in patients with severe P. falciparum malaria when compared with controls (P < 0.0001) or with patients with non-severe malaria (P = 0.0009)." (PMID 18194515, 2008). "Although the literature connecting the pro-inflammatory cytokines other than TNF to malaria is as yet much smaller than that for TNF, this does not imply that their potential for understanding this disease is correspondingly minute." (PMID 17029647, 2006). "In brief, it suggests that sequestration favours the brain when circulating concentrations of TNF are high (ie when the patient is ill), but not before onset of illness, or in malaria tolerant individuals." (PMID 17029647, 2006). "The plasma levels of TNF-α and IL-10 were comparable to those in normal Ghanaian children without symptoms of malaria or detectable parasitaemia." (PMID 16321150, 2005). "The proinflammatory cytokines: TNF‐α (p < .001), IFN‐ɣ (p < .001), IL‐1β (p < .001), IL‐6 (p < .001), GM‐CSF (p < .001), and the anti‐inflammatory cytokine IL‐10 (p < .001) levels were significantly higher in malaria‐infected males and females than in their counterparts without malaria." (PMID 39240033, 2024). "In this context, it is possible to speculate that during EBV reactivation, the virus induces high secretion of cytokines such as TNF-α, IL-12p40, IL-10, and IFN-γ, which could exacerbate the immune response to malaria and contribute to uncontrolled proliferation of the parasite." (PMID 39133703, 2024). "IL-1β and TNF-α are pyrogens cyclically released by monocytes, macrophages, and neutrophils that participate in universal mechanisms of systemic inflammation and febrile response in infectious and noninfectious diseases, such as malaria and cancer." (PMID 38774541, 2024). "Furthermore, previous studies showed higher IL-10/TNF-α levels in children with severe malaria than in those with a non-severe disease, and these cytokines were also higher in patients who died than in those who survived." (PMID 36668942, 2023).